EGFR (epidermal growth factor receptor)
Diseases named in the same sentence as EGFR in open-access papers (continued):
Sharing a sentence is not in itself a finding about the gene and the disease.
tumor (continued). "Although a significant relationship between the tumor glucose metabolism level depicted on PET images and EGFR mutation profiles has been reported in several works, traditional PET-derived semiquantitative indexes show insufficient ability to be widely used in clinical practice." (PMID 35800046, 2022). "Existing clinical trials also suggested that tumor subtypes affected response rate, toxicity, and progression-free survival of targeted agents such as bevacizumab, pemetrexed, and epidermal growth factor receptor tyrosine kinase inhibitors (EGFR-TKIs)." (PMID 35655730, 2022). "Besides VEGF family, tumor angiogenesis is also tightly regulated by numerous endogenous factors like epidermal growth factor receptor (EGFR) and fibroblast growth factor (FGF)." (PMID 35372044, 2022). "Likewise, cancer-cell derived exosomes having copious presence of Ras and other kinases in the MAP kinase pathway, phosphorylated EGFR, and other growth factors led to an increased longevity of tumor monocytes." (PMID 36032679, 2022). "Moreover, anti-EGFR functionalized Fe2O3 nanoparticles can be used as magnetic resonance imaging contrast agents for tumor diagnosis." (PMID 36096856, 2022). "In addition, a high-fat diet can produce secondary cholic acid, affecting mitosis, activating NF-κB and epidermal growth factor receptor (EGFR) and promoting tumour development." (PMID 35749000, 2022). "Whether these effects on epithelial architecture modulate EGFR-RAS-ERK activation (perhaps through altering SCRIB/DLG1 function) or affect other signaling pathways to contribute to the tumor suppressor function of Tsp29Fb/TSPAN6 needs to be examined." (PMID 35184157, 2022). "However, among those who were tested, EGFR mutation was found in 7% (30/423), ALK translocation in 1% (6/411), and PD-L1 tumor proportion score ≥ 50% in 39% (156/399)." (PMID 35621649, 2022). "EGFR-TKIs may be less effective when local tumor inflammation is severe, which may account for the lower efficacy of osimertinib in patients with ultra-short fragments." (PMID 35941190, 2022). "Our qRT-PCR findings revealed significant expression of EGFR in HCC tumor tissues (T)." (PMID 35999564, 2022). "This suggests that elacridar coadministration could be considered to enhance the brain (and tumor) penetration of EAI045 in patients suffering from suitable EGFR mutant brain metastases." (PMID 36145346, 2022). "NK cells, can be primed and modified ex vivo, in a similar manner to CAR-T cells, to express a CD38-CD3ξ domain required for NK cell signaling and scFv antibody fragments to introduce specificity to a range of diverse tumor antigens, including those targeting the cell-surface EGFR or/and EGFRvIII." (PMID 36185288, 2022). "The size of the tumor at autopsy is shown by the EGFR immunohistochemistry." (PMID 35745855, 2022). "Lidocaine with 0.5 mM concentration could decrease the expression of EGFR by upregulating the level of colorectal cancer cells and miR-520a-3p (retinoblastoma cell line) and inhibit the proliferation of tumor cells." (PMID 35966857, 2022). "Our results suggest that exosomes can be used therapeutically to target EGFR-expressing tumor." (PMID 36114463, 2022). "In addition, tumor cell-targeted PDT was developed by injection of EGFR-targeted PS followed by tumor-restricted irradiation." (PMID 35635308, 2022). "The epidermal growth factor receptor (EGFR) plays a crucial role in tumor cell activity." (PMID 36556296, 2022). "However, the coexistence of EGFR and KRAS mutations has been demonstrated in rare cases by tumor tissue testing, thus excluding that this phenomenon is only related to CHIP." (PMID 36010306, 2022). "Finally, some anti-tumor effect observed with BATs was a result of anti-EGFR signaling, especially given the presence of intact EGFR signaling for both CT26EGFR and HT-29." (PMID 35177811, 2022). "EGFR, a well-known cancer promoter factor, facilitates tumor cell proliferation and migration." (PMID 34991461, 2022).
tumor (continued). "Moreover, microfluidic-based nanoparticles showed significant downregulation of EGFR (epidermal growth factor receptor) mRNA and protein expression levels in vitro and in vivo and significant tumor growth inhibition." (PMID 35057037, 2022). "EGFR-TKI changes the tumor immune microenvironment, for example, by triggering programed death ligand-1 (PDL-1) expression and CD8 T-cell infiltration accompanied by tumor oncogenic mutations." (PMID 36612121, 2022). "Therefore, miR-30a-5p in combination with other EGFR-TKI agents increased tumor cell drug sensitivity." (PMID 35264191, 2022). "EGFR is overexpressed in tumor cells and is involved in angiogenesis, invasion, and metastasis." (PMID 36714624, 2022). "First, the direct effect of anti-EGFR antibodies was explored on tumor cells without mutations in EGFR signaling pathways (referred to as EGFR wild-type)." (PMID 35035479, 2022). "Similarly, frequent expression of GPC3 was found in tumours that were positive for EGFR (22.4%, 11 cases) and Ki67 (11.4%, 13 cases)." (PMID 36676710, 2022). "In our previous paper, we discussed that pan-HER targeting might decrease tumor resistance to EGFR targeted therapy because EGFR receptors show crosstalk with HER2, which plays key roles in resistance in Tras-R cells." (PMID 35248049, 2022). "Whether it can contribute to the modification of the tumor microenvironment, drug resistance to EGFR-TKI, or immunotherapy remained to be discovered." (PMID 35600359, 2022). "LCRT for primary tumor and all oligometastatic sites in elderly patients with oligometastatic NSCLC harboring EGFR activating mutations during first-line EGFR-TKIs treatment may improve their survival outcomes with tolerable toxicity." (PMID 35145913, 2022). "The significant difference in tumor status between the CT + TT and CC genotypes in EGFR wild-type patients was also observed in an evaluation of all patients, in which 43.9% with the CT + TT genotype had more advanced (T3/T4) tumors compared with 27.8% with the CC genotype (p = 0.016)." (PMID 36429891, 2022). "Interestingly, anchorage-independent growth, migration, and xenograft tumor growth were increased when either EGFR or EphA2 was overexpressed, but these effects were dependent on the presence of Ephexin1." (PMID 35668076, 2022). "We demonstrated that EGFR wt with SRGN over-expression patients was displayed as inflamed tumors, but associated with “cancer-promoting inflammation”, which shaped TME toward a tumor-permissive state by chronic inflammation and immune evasion." (PMID 35432532, 2022). "Given the significant associations between elevated EGFR mRNA and protein phosphorylation levels, TERTp mutation and TERT expression in tumor tissue from patients with GBM, we tested for a potentially causal relationship using three independent experimental approaches." (PMID 36130485, 2022). "However, it is inevitable that drug resistance develops after 10 months of medication, and some experiments have demonstrated that EGFR resistance achieves tumor escape by up-regulating PD-L1 expression and inhibiting T cells." (PMID 36313314, 2022). "However, YTHDF2 functioned as a tumor suppressor in HCC via destabilization of epidermal growth factor receptor (EGFR) mRNA89, leading to the inhibition of the ERK/MEK signaling pathway in HCC." (PMID 36446846, 2022). "Lower MTV combined with non-smokers and a peripheral tumor location were more likely to have EGFR mutations." (PMID 36276079, 2022). "Interestingly, the EGFR mutant lung cell lines showed more sensitive to the drugs targeting EGFR on the 3D tumor model." (PMID 36313330, 2022). "REGN1400 in combination with anti-EGFR or anti-HER2 antibodies inhibits tumor growth more potently." (PMID 36271429, 2022). "Randall and colleagues used MALDI imaging for a quantitative map distribution of EGFR inhibitor and tumor characteristics in a patient-derived xenograft model, which could possibly help to analyze the reasons for drug resistance." (PMID 36230481, 2022).
tumor (continued). "STAT3 and AKT proteins are known downstream targets of EGFR as well as promoters of tumor growth." (PMID 35499593, 2022). "The stability of the transformed state in vitro is intriguing and could allow for a double bind therapeutic strategy where the goal is to switch between cell states EMT-MET to keep the tumor from rapidly escaping targeted therapies, such as EGFR inhibitors." (PMID 35804837, 2022). "In the absence of cell adhesion, normal cells lose expression of EGFR and induce apoptosis; by contrast, tumor cells do not exhibit loss of EGFR during detachment." (PMID 36230714, 2022). "The benefit from the combination of first-generation EGFR-TKIs and chemotherapy might be attributed to the synergistic effect with EGFR-TKIs on the tumor growth of NSCLC." (PMID 35525919, 2022). "EGFR has also been explored as a target for CAR-T therapy, and clinical trials have been undertaken using ABDs specific for either the WT or a mutated tumor-specific form of the receptor known as EGFRvIII." (PMID 35935988, 2022). "In our HNSCC cell lines, gene amplification and/or protein overexpression of EGFR may be responsible for similar epigenetic changes and could serve to silence important tumor suppressor genes." (PMID 35224804, 2022). "This study aimed to investigate the in vivo efficacy of various doses of KO supplementation on the inhibition of CRC tumour growth, molecular markers of proliferation, angiogenesis, apoptosis, the epidermal growth factor receptor (EGFR) and its downstream molecular signalling." (PMID 35120511, 2022). "This provides an opportunity to re-challenge the tumor with anti-EGFR antibodies." (PMID 35280779, 2022). "In the autoradiography of the tumor sections, the accumulation of 111In-cetuximab correlated closely with the immunohistochemical distribution of EGFR, indicating that imaging uptake can reflect actual EGFR expression of the tumor." (PMID 35962347, 2022). "Notably, anti-EGFR agent-induced rash can be a useful surrogate predictive marker for a substantially improved OS, progression-free survival (PFS), and tumor response to several EGFR inhibitors approved for clinical use." (PMID 36269747, 2022). "High SUVmax, CEA levels, and a non-spiculated tumor margin were independent predictors of the EGFR mutation." (PMID 36276079, 2022). "Moreover, upon treatment of the conjugates with therapeutic light, EGFR-inhibitory activity was recovered that attenuated EGFR signal-dependent tumor cell proliferation." (PMID 36232384, 2022). "In non-tumor cells, EGFR-OSMR can be activated synergistically by the ligands EGF and OSM." (PMID 35954323, 2022). "We therefore conducted a comparative investigation of targeting DDR1 in combination with EGFR inhibitor (lapatinib), utilizing an additional tumor model of GBM and including the brain penetrable DDR1/BCR-ABL inhibitor nilotinib to evaluate its combinatorial efficacy." (PMID 35664781, 2022). "The authors also reported that G1 inhibited tumor growth of HCC xenografts by activating GPER/EGFR/ERK signaling, indicating that the pharmacological activation of GPER could be a viable therapeutic strategy for HCC patients." (PMID 36558071, 2022). "EGFR is abnormally upregulated or activated in a variety of tumours." (PMID 35814459, 2022). "Moreover, compared to single-agent treatment, dual blockade of MET and EGFR resulted in enhanced reductions in the tumour volume and downstream signaling in vivo." (PMID 35101055, 2022). "Additionally, tumor laterality still influenced OS when confounders were balanced with PSM or when patients receiving anti-EGFR agents or with EHD were excluded from the analysis." (PMID 36406356, 2022). "The expression of UTX in tumor tissue was correlated with the phosphorylation of EGFR." (PMID 34661759, 2022). "Taspine could antagonize the EGFR signaling pathway to reduce cell proliferation and migration and inhibit xenograft tumor formation." (PMID 35269825, 2022).
tumor (continued). "Our central hypothesis was that the ELP-EGF construct would bind to EGFR+ tumor cells with high affinity to enable NIR detection." (PMID 36082359, 2022). "We planned to analyse the expression of EGFR in the tumour in at least 50% of the cases under study, already foreseeing the difficulty of accessing this material since many patients undergo biopsy or undergo surgery in other services and then are referred to our centre for treatment." (PMID 36158981, 2022). "EGFR UniCARs have been successfully used both in vitro and in vivo to eliminate tumours." (PMID 35205725, 2022). "Recently, several studies indicated that EGFR has a pathological role in non-neoplastic diseases." (PMID 35877429, 2022). "By incorporating miRNA mimics of the tumor suppressor miR-16 in minicells covered with epidermal growth factor receptor (EGFR) antibodies, MesomiR-1 could target tumor cells accurately." (PMID 35909469, 2022). "Among these survival-related genes, 33 genes had higher expression in tumor tissues than in normal tissues like EGFR, AKT1, and HSP family genes, suggesting they could serve as diagnostic markers to distinguish normal from tumoral samples." (PMID 35873484, 2022). "Tumor resection could increase treatment efficacy of epidermal growth factor receptor (EGFR)-tyrosine kinase inhibitors (TKI) in patients with advanced EGFR-mutant non-small cell lung cancer (NSCLC)." (PMID 36581631, 2022). "The RGO was functionalized with PEG, CPSS (carbon porous silica nanosheets), Au nanosheets, R6G, (Rhodamine 6G a Raman reporter), and anti-EGFR (epidermal growth factor receptor for targeting tumor) for sensitive low-powered laser-efficient NIR PT therapy against A549 and MRC-5 cells." (PMID 36080351, 2022). "EGFR mutations cause abnormal activation of the downstream JAK/STAT3 signalling pathway, leading to increased expression of phosphorylated STAT3, followed by abnormal tumor growth, angiogenesis, invasion, and metastasis." (PMID 36185620, 2022). "MiR-497 may influence tumor cell responsiveness to chemotherapy and tumor cell resistance to EGFR-TKI via IGF1R targeting and AKT activation." (PMID 35264191, 2022). "It was also reported that the DRD2 agonists could exert anti-tumor effects through ROCK-mediated inactivation of Cofilin-1 or inhibiting EGFR/AKT/MMP-13 pathway." (PMID 35463319, 2022). "CD73 blockade markedly inhibited tumor growth in a mouse model of EGFR-mutant NSCLC." (PMID 35935943, 2022). "In addition, a high C:N ratio (the ratio of the contrast-enhancing volume to the necrotic tumor volume) resulted as correlating with overexpression of the gene EGFR." (PMID 36551961, 2022). "However, baseline data from other groups showed that tumoral B7-H3 expression was higher in males, smokers, and more frequent in NSCLC patients with poor differentiation, larger tumor size, and wild-type EGFR." (PMID 35590371, 2022). "Finally, the expression of EGFR and P-EGFR in tumor tissues was characterized by IHC to show the activity of the relevant signaling pathways." (PMID 35105871, 2022). "Moreover, we examined several factors involved in EMT since the EMT is a crucial step for EGFR-induced tumor metastasis." (PMID 35501907, 2022). "With regard to tumor histology, our model was novel in the incorporation of EGFR mutation status in nonsquamous NSCLC, which is a genetic feature identified with prognostic significance." (PMID 34927371, 2022). "Preclinical evidence shows that the activation of the EGFR signaling pathway may promote tumor cell PD-L1 expression; theoretically, targeted therapy combined with immunotherapy can help enhance antitumor activity." (PMID 35159131, 2022). "However, problems have arisen because almost all patients with dramatic initial responses to the first-generation EGFR-TKIs ultimately showed tumor progression and inevitably became resistant within 6–12 months." (PMID 35931945, 2022).
tumor (continued). "Since both microglia and GBM express EGFR, EGF may serve as a paracrine factor to recruit TAMs to the tumor sites, and at the same time, it binds to EGFR of GBM to stimulate GBM invasion." (PMID 35967394, 2022). "The EGFR exon 19 deletions were present in only 3 tumor samples in our cohort of 60 patients." (PMID 35681771, 2022). "However, 55 of the 109 individuals assigned to subtype 2 show chr7 gain (and, hence, amplification of the EGFR) and chr10 loss, which leads to deletion of the PTEN gene, a known tumor suppressor." (PMID 35211690, 2022). "Knowing that EGFR signaling pathway regulated tumor sphere formation and autophagy, whether activation of EGFR pathway altered autophagy-associated networks was investigated." (PMID 35725558, 2022). "This could be one mechanism underlying how EGFR inhibition increases CD8+ T-cell infiltration in EGFR-driven tumours that we observed." (PMID 36010935, 2022). "In a study, higher values of relative cerebral blood volume in the nonenhancing region of the tumor (rCBVNER) in the EGFR-wildtype GBM patients was suggested to be associated with poorer survival." (PMID 35610333, 2022). "Our omics analysis of clinical data from cohorts of NSCLC revealed that dysregulation of EGFR/MAP2K1/MTOR/YAP1 signaling pathways are associated with disease progression, anticancer drug resistance, tumor immune infiltration, immune-invasive phenotypes and worse prognosis of the cohorts." (PMID 35655775, 2022). "On-target off-tumor and off-target toxicities to EGFR signaling inhibitors are of concern and may have a significant impact on patient quality of life and treatment effectiveness." (PMID 36185288, 2022). "EGFR (Epidermal growth factor receptor) plays an important role in the regulation of the proliferation, differentiation, survival and motility of the tumor cells and was found to be highly expressed in over 60% of NSCLCs, which indicates that it has the potential to promote NSCLC metastasis." (PMID 35807355, 2022). "Therefore, the over-expression of EGFR is an excellent target for developments of tumor imaging agent." (PMID 35120180, 2022). "According to this hypothesis, EGFR signaling changes during tumor progression, and while EGFR is overexpressed in primary tumors, metastatic cells become intrinsically resistant to EGFR targeted therapy." (PMID 35163586, 2022). "An explanation for these results could be the downregulation of PD-L1 on tumour cells, mediated indirectly by oncogenic EGFR signalling via IRF1." (PMID 36010935, 2022). "The first study evaluating the tumor-targeting potential of [O-methyl-11C]PD153035 was carried out in immunodeficient male WAF rnu/rnu rats xenografted with the neuroblastoma cell line SH-SY5Y observed to express high levels of EGFR." (PMID 35455447, 2022). "EGFR-TKIs, as competitive inhibitors of adenosine triphosphate (ATP) in the TKIS domain of EGFR, inhibit abnormal proliferation and differentiation of tumor cells by inhibiting EGFR and blocking its downstream signal transduction, and ultimately inhibiting tumor growth and progression." (PMID 34964410, 2022). "Furthermore, when ZEGFR:03115 was radiolabelled with zirconium-89, only very low accumulation of the radioconjugate was found in tumours with low EGFR expression levels." (PMID 35057796, 2022). "This can be explained by the low level of EGFR activation in this tumor sample." (PMID 36376325, 2022). "Considering the fundamental role of EGFR in maintaining the homeostasis of healthy tissue, it is not surprising that EGFR gain-of-function mutations are often detected in some tumor types." (PMID 36185288, 2022). "Moreover, the EGFR promotes immune escape by tumor cells through the inhibition of the cytotoxic activity of T cells." (PMID 35216384, 2022). "Besides, Pseudomonas fluorescens lectin (PFL) inhibited neovascularization in a dose-dependent manner and downregulated the integrin and epidermal growth factor receptor, inhibiting in vitro and in vivo tumor growth." (PMID 36530430, 2022).